PDK1 (pyruvate dehydrogenase kinase 1)
Diseases named in the same sentence as PDK1 in open-access papers (continued):
Sharing a sentence is not in itself a finding about the gene and the disease.
breast cancer (continued). "Glycolysis gatekeeper PDK1 could reprogram breast cancer stem cells under hypoxia." (PMID 36531021, 2022). "Interestingly, the finding that overexpression active forms of AKT in PDK1-knockdown breast cancer cells are unable to rescue anchorage-independent growth indicates that PI3K could also be activated by PDK1, which is the downstream target of Ras/ERK signaling." (PMID 34145217, 2021). "Similarly, H19 is responsible for glycolysis and maintenance of breast cancer stem cells thanks to its ability to bind to let-7 miRNA, releasing hypoxia-inducible factor 1α and increasing the expression of pyruvate dehydrogenase kinase 1, protein highly expressed in breast cancer stem cells." (PMID 34439740, 2021). "Furthermore, GW501516 increased PPARβ/δ and PDK1 expression in mammary tumors." (PMID 32375405, 2020). "The results of our study suggest that the PDK-1 signaling pathway might be a promising therapeutic target for the treatment of breast cancer and that PDK1 expression should be tested in addition to PIK3CA status in patients with breast cancer prior to beginning therapy." (PMID 24739482, 2014). "Overall, SLC influences oxidative phosphorylation via the PDK1/PDHA1 and SIRT1/PGC-1α/NRF1/TFAM signaling pathways and downregulates the HER2 pathway, thereby ultimately inhibiting HER2-positive breast cancer progression." (PMID 41465397, 2025). "In mammary epithelial cells and breast cancer cells, PI3K and phosphoinositide‐dependent kinase (PDK1) act as upstream negative regulators of LATS1/2, thereby promoting YAP nuclear localization, and PI3K inhibitors block YAP nuclear localization." (PMID 40661662, 2025). "In summary, our study revealed the mechanism by which EMC2 promotes breast cancer progression and identified EMC2 as a drug target for PDK1/AKT inhibition." (PMID 40303285, 2025). "This study reveals the EMC2/USP7/ENO1/B-MYB protumorigenic axis in breast cancer and identifies EMC2 as a candidate target for PDK1/AKT inhibitory therapy." (PMID 40303285, 2025). "In breast cancer, dual inhibition of FTO and the PDK1-AKT signaling pathway using FB23 and BX-912 has been shown to significantly reduce tumor progression." (PMID 41281757, 2025). "In this study, we have highlighted the significance of TGFβ-1, IL19, CXCR4, BMP1, IL1A, VCAN, PDK1, and WNT2 in breast cancer pathology." (PMID 41348904, 2025). "In summary, this study suggests that the herbal recipe SLC has the potential to act as an agent for inhibiting OXPHOS through the PDK1/PDHA1 and SIRT1/PGC-1α/NRF1/TFAM signaling axis to treat HER2-positive breast cancer." (PMID 41465397, 2025). "Of note, a correlation analysis between PDK1 and HDAC levels in breast cancer samples from the Cancer Genome Atlas (TCGA) dataset highlighted that high HDAC-2 expression had a poor OS probability." (PMID 38201636, 2024). "Concurrently, PDK1, as a classical downstream target gene of HIF-1a, formed a positive feedback loop with HIF-1a to promote the progression of breast cancer." (PMID 38560503, 2024). "Our model predictions show that PDK1 is the most effective target enhancing the antitumor activity of BYL719 in sensitive and resistant T47D breast cancer cells." (PMID 38273040, 2024). "We analyzed the expression of PDK1 in the GSE65194, GSE33447, and GSE45827 datasets to elucidate the cancerogenic role of PDK1 in breast cancer." (PMID 38560503, 2024). "We also performed experiments using another breast cancer cell line, MCF-7, to analyze the correlation between CRY1 and PDK1 proteins." (PMID 38199564, 2024). "Additionally, AKT1-3 mutations and/or amplifications, PDK1 amplification, PTEN and TSC1/2 inactivating mutation, and deletion or epigenetic silencing, which cause hyperactivation of the pathway, have also been found in breast cancer and have been suggested to hold prognostic or predictive value." (PMID 36901954, 2023).
breast cancer (continued). "We found that levels of PDK1 in MCF7 and MDA-MB-231 breast cancer cells were significantly higher than those in immortalized normal MCF10A breast cells." (PMID 35892859, 2022). "The degradation of HIF-1α accelerates the reversal of the expression of glycolysis-related proteins GLUT1, PDK1, and HK2 in cancer cells, which weakens the glycolysis of breast cancer cells and indirectly leads to tumor growth inhibition." (PMID 35350760, 2022). "Hypoxia-induced occupancy of the ANGPTL4 and PDK1 HREs by TRIM28, KU70, KU86, DNA-PKcs, and HIF-1α was also observed in SUM159 human breast cancer cells." (PMID 35031618, 2022). "In this study, we elucidate that these epigenetic alterations play a vital role in regulating PDK1 and identify the new regulation axis of EZH2/HDAC2/miR-148a/PDK1 in breast cancer progression and therapeutic resistance." (PMID 35892859, 2022). "Moreover, PDK1 may be involved in breast cancer metastases to the liver." (PMID 35892859, 2022). "We found that Adriamycin-resistant breast cancer cell line MCF7/ADR not only had lower levels of miR-148a expression, but also higher levels of PDK1 expression compared to the control (MCF7)." (PMID 35892859, 2022). "For example, the treatment of breast cancer cells with PI3K or AKT inhibitors results in increased expression and the activation of SGK3, which depends on hVps34 for activation by PDK1 and mTORC242." (PMID 33960177, 2021). "Knockdown of PDK1 is reported to impede tumor growth in nude mice in HNSC, melanoma, and breast cancer cells." (PMID 32071289, 2020). "In liver-metastasis prone breast cancer cells, HIF-1α triggers the glycolytic phenotype required for migration by directly expressing the enzyme pyruvate dehydrogenase kinase 1 (PDK1)." (PMID 33266219, 2020). "Gasser and colleagues have also shown that INPP4B over-expression leads to enhanced SGK3 activation in ZR-75-1 breast cancer cells, triggering a switch from AKT- to SGK-dependent signaling downstream of PDK1." (PMID 32630372, 2020). "In the current study, we found that mRNA levels for two of the four PDK isoforms (PDK1 and PDK3) are upregulated in the TNBC and basal-like breast cancer subtypes." (PMID 33316932, 2020). "The HIF-1α-inducible expressions of GLUT1, HK2, PDK1, and LDHA were low in NRF2-silenced breast cancer cells and, accordantly, levels of hypoxia-inducible glycolysis metabolites such as G6P, F16P, GAP, and lactate were diminished by NRF2-silencing." (PMID 31078780, 2019). "Taken together, our studies identify a novel role and regulatory mechanism of PDK1 in BCSC reprogramming, which provides a promising strategy for breast cancer therapy." (PMID 29106390, 2018). "Quantitative RT-PCR data showed that silencing P4HA1 in breast cancer cells significantly reduced mRNA levels of LDHA and PDK1 under normoxia and hypoxia conditions." (PMID 30367042, 2018). "The components of the PI3K/Akt and MAPK pathways, including GSK3β, PDK1, and c-RAF have been reported to be involved in breast cancer progression." (PMID 27527857, 2016). "Combined treatment of γ-tocotrienol with PPARγ antagonists was found to reduced PI3K, phosphorylated PDK-1 (active), and phosphorylated-Akt (active) levels in MCF-7 and MDA-MB-231 breast cancer cells." (PMID 23431460, 2013). "The mutational and mRNA expression status of PIK3CA, PIK3R1 and AKT1, and expression status of other genes involved in the PI3K pathway (EGFR, PDK1, PTEN, AKT2, AKT3, GOLPH3, WEE1, P70S6K) were assessed in a series of 458 breast cancer samples." (PMID 24229379, 2013). "Combined treatment with the same doses of these agents resulted in a significant decrease in phospho-Akt, PDK-1, and PI3K levels as compared to MDA-MB-231 breast cancer cells in the vehicle-treated control group." (PMID 23431460, 2013).
breast cancer (continued). "In HER-2-overexpressed breast cancer, ErbB2 activates NF-κB via signaling that includes PI3K, PDK1, Akt, protein kinase 2 (CK2), and CKBBP1." (PMID 21876713, 2012). "In particular 2-O-Bn-InsP5 increases the effect of tamoxifen in breast cancer cells MCF7, consistent with the reported role of PDK1 inhibition in tamoxifen sensitisation." (PMID 20051961, 2010). "Of the three breast cancer cell lines, two (MDA-231 and MCF-7) demonstrated an increase in PDK-1 mRNA and protein expression in hypoxia." (PMID 18542064, 2008). "The growth characteristics of Comma/vector cells mirrored those of human breast epithelial cell line MCF-10A, whereas those of Comma/PDK1 were similar to MCF-7 and MDA-MB-231 breast cancer cells." (PMID 16551362, 2006). "In addition, Comma/PDK1 cells formed invasive adenocarcinomas in syngeneic mice, and was highly expressed in 90% of invasive human breast cancers, suggesting that PDK1 may serve as a prognostic indicator of metastasis, as well as a potential therapeutic target." (PMID 16551362, 2006). "WDNM1, a putative breast cancer metastasis suppressor, was reduced 26-fold, and the MMP-2 inhibitor, TIMP-3, was also decreased in Comma/PDK1 cells." (PMID 16551362, 2006). "Of note were the similar invasion activity between Comma/PDK1 cells and MDA-MB-231 breast carcinoma cells, which are known for their metastatic behavior." (PMID 16551362, 2006). "However, our observation as frequent deregulation in the PDK-1/AKT/mTOR/p70S6K signalling pathway and its prognostic role in breast cancers implicated the notion of using inhibitors to impair this pathway and to provide additional strategy to treat breast cancer." (PMID 16288304, 2005). "To further confirm our investigation on increased phosphorylation in breast cancers, we have applied IHC staining on breast tumours fixed on TMA slides to examine the phosphorylation status of PDK-1, AKT, mTOR, p70S6K, S6, Stat3, and EGFR." (PMID 16288304, 2005). "PDK1 and HIF-1α form a positive feedback loop to promote breast cancer progression." (PMID 38560503, 2024). "Notably, liver-metastatic breast cancer cells have high HIF-1α activity, which induces PDK1 expression and glycolysis, and knockdown of HIF-1α or PDK1 inhibits breast cancer liver metastasis." (PMID 37444501, 2023). "Specifically in breast cancer, the oncogenic transcription factor c-Myc reprograms the cellular metabolism towards aerobic glycolysis by directly transactivating a number of glycolytic genes, including GLUT1, HK2, PDK1, and LDHA." (PMID 37508533, 2023). "In addition, it was shown that ribociclib, combined with PDK1 inhibitor GSK2334470 or the PI3K inhibitor alpelisib, decreased ER+ breast cancer xenograft tumor growth more efficaciously than either drug alone." (PMID 35892870, 2022). "In conclusion, miR-361-5p inhibits glycolysis in breast cancer cells and FGFR1, a miR-361-5p target, reverts the anti-glycolytic function of those small RNAs and represses OXPHOS by upregulating LDHA and pyruvate dehydrogenase kinase-1 (PDHK1) function." (PMID 35348905, 2022). "It was demonstrated that knocking-down HIF-2α in MDA-MB-231 breast cancer cells significantly decreased the expression of glycolysis-related gene products, such as HK2, LDHA, SLC2A1 and PDK1, consisting with the suppression of mRNA levels of glycolysis- and hypoxia-related genes." (PMID 35096814, 2021). "To test this hypothesis, we used breast cancer cell lines (MCF-7 and MDA-MB-231), and we analyzed the expression of HIF-1α, PDK1, PDH, SIRT1, SIRT3, and ROS for mitochondrial metabolic pathway." (PMID 34771733, 2021). "PDK1, a HIF-1α target that antagonizes the function of PDH, a main rate-limiting enzyme for pyruvate converting to acetyl-coA and entering the TCA cycle, has been reported to be a critical regulator of breast cancer metabolism and metastasis." (PMID 33489906, 2020).
breast cancer (continued). "Dichloroacetate (DCA) can enhance metformin-induced oxidative damage with simultaneous reduce of metformin promoted lactate production through PDK1 inhibition, suggesting the innovative combinations, such as metformin and DCA, will be promising in expanding breast cancer therapies." (PMID 33489906, 2020). "In a subset of breast cancer cell lines, hyperactivation of PI3K pathways was reported to be independent from Akt activation and it was shown that tumourigenicity of the cells, as assessed by anchorage-independent growth, was dependent on PDK1 and SGK3." (PMID 31088502, 2019). "A metastatic role of PDK1 in breast cancers was demonstrated to be independent of Akt activation in cell culture systems." (PMID 29668719, 2018). "For example, evidence suggests that mTORC1 signaling in BYL719 resistant breast cancer cell lines HCC1954 and JIMT1 is a consequence of the higher activity of SGK and PDK1 in these cell lines, which is sufficient to activate mTORC1 through the phosphorylation of TSC2 by SGK." (PMID 29623959, 2017). "Given that NVP-BEZ235 is a poor inhibitor of AKT and PDK1, and inhibition of mTOR by AZD8055 prevents the activation of both AKT-T308 and AKT-S473, in our model AZD8055 is a better treatment for breast cancer." (PMID 25436981, 2014). "In mammary carcinoma cells expressing high levels of FABP5, FABP5 delivers RA to PPARβ/δ, enhances the transcriptional activity of PPARβ/δ and activates PPARβ/δ target gene, PDK1 and VEGF-A." (PMID 25260874, 2014). "Importantly, similar results were obtained using Western blottings demonstrating that PDK-1 phosphorylayion levels were remarkably elevated in MCF-7 and MDA-MB-468 breast cancer cell lines compared to HMEC and MCF-10A cells." (PMID 16288304, 2005). "Elevated phosphorylation of PDK-1, mTOR and increased AKT kinase activity in both MDA-MB-468 and MCF-7 breast cancer cell lines indicated that they may play important roles in breast carcinogenesis." (PMID 16288304, 2005). "Interestingly, we have shown the phosphorylation of AKT on T308 resembled well with that of PDK-1 in breast cancer, which agreed with other results demonstrating residue T308 of AKT was directly phosphorylated by PDK-1." (PMID 16288304, 2005). "Although PDK-1 is an upstream kinase of AKT and transfection of PDK-1 cDNA can induce transformation of cells, the activation of PDK-1 has not been demonstrated in primary breast carcinoma, yet." (PMID 16288304, 2005). "Furthermore, PDK1 is a direct transcriptional target of hypoxia-inducible factor 1-alpha (HIF-1α), establishing a mechanistic link between hypoxic conditions and glycolytic reprogramming in breast cancer." (PMID 41465397, 2025). "Additionally, in NF‐κB‐activated cancers, in particular breast cancer, inhibition of the NF‐κB pathway with its inhibitors could promote CTR1‐copper upregulation, thus elevating MEK‐ERK and PDK1‐AKT pathways to form acquired resistance to NF‐κB inhibitors." (PMID 40999870, 2025). "It was experimentally demonstrated that HIF-1α under hypoxic conditions induced PDK1, a downstream target gene of HIF-1α, which promotes protein stability and transcriptional activity of HIF-1 α, forming a positive feedback loop that promotes breast cancer progression." (PMID 38560503, 2024). "Studies have shown that PDK1 increases HIF-1α protein stability by phosphorylating HIF-1α Ser451 and promotes HIF-1α’s transcriptional activity by increasing HIF-1α’s binding to P300, and PDK1 and HIF-1α form a positive feedback loop to promote breast cancer progression." (PMID 39199957, 2024). "Furthermore, HIF-1α phosphorylation at serine 451 was detected in wild-type breast cancer cells but not in PDK1 knockout breast cancer cells." (PMID 38560503, 2024). "Additionally, Prox1 represses PDK1 and induces MPC1 in breast cancer cells." (PMID 37508533, 2023).
breast cancer (continued). "BA could inhibit c-myc-induced glycolytic activation and inhibited protein expression of c-Myc, LDHA, and p-PDK1/PDK1 in MCF-7 and MDA-MB-231 cells in vitro and mice breast cancer model suggested that BA is a good candidate for the glycolysis inhibitor in vivo." (PMID 36339566, 2022). "Using transcriptome sequencing data of the CSC subpopulation in SUM149 human breast cancer cell line from GSE132083, we compared the glycolytic gene expression profiles between the CSC group and non-CSC group, and found that SLC2A1, HK2, ALDOA, ENO1, LDHA and PDK1 were upregulated in the CSC group." (PMID 34052833, 2021). "Notably, the upregulation of PDK1 and PDK3 in breast cancer patients could be correlated with higher Ragnum and Buffa hypoxic scores." (PMID 33316932, 2020). "3-phosphoinositide dependent protein kinase-1 (PDK1), a transducer protein that functions downstream of PI3K, is responsible for the regulation of cell proliferation and migration and it also has been found to play a key role in different cancers, pancreatic and breast cancer amongst others." (PMID 31683659, 2019). "However, PDK1 has been reported to regulate breast cancer growth in Akt-independent manner also in absence of PIK3CA mutations." (PMID 28287465, 2017). "In addition to this, another study showed that although breast cancer cells growth is independent of PDK1, their ability for tumour initiation in vitro relies on it, regardless of their PIK3CA burden." (PMID 29064423, 2017). "In this context, unlike bone or lung metastatic cells, liver metastatic breast cancer cells exhibit a unique metabolic program, characterized by increased hypoxia inducible factor 1α (HIF1α) activity and enhanced expression of its target, PDK1." (PMID 28356139, 2017). "In contrast, phosphorylation of PDK1 at Ser241, which induces a cancer stem cell gene expression signature, was negatively correlated with CD47 mRNA expression and was the fourth most significant change in protein phosphorylation in the breast cancer dataset (p = 0.0015)." (PMID 26840086, 2016). "For example, PDK1, but not AKT, is activated in some breast cancers with PIK3CA mutations." (PMID 22666248, 2012). "However, the elevated phosphorylation on mTOR and Stat3 was noticeably differed from that on PDK-1 in various stages of breast cancer, indicating these molecules are not in a single linear signalling cascade regulated by PDK-1." (PMID 16288304, 2005). "Similarly, animals treated with the PPARδ agonist GW501516 exhibited an accelerated formation of breast cancer tumors, particularly adenosquamous and squamous cell carcinomas, and tumors of mice treated with GW501516 exhibited increased levels of PPARδ and activated PDK1." (PMID 37251321, 2023). "Thus, not all PIK3CA-mutated breast cancer models might benefit from AKT blockers, as some may promote cell growth through an AKT-independent axis, such as PDK1/SGK3/mTORC1." (PMID 36901954, 2023). "Although the promoting effect of PPARβ/δ on breast cancer is partially dependent on the PDK1 signaling pathway, studies showed that PDK1 is not a target gene of PPARβ/δ, which further reveals the correlation between the two may be mediated by some factors in other signaling pathways." (PMID 36611922, 2022). "In addition, our study also shows that this novel PDK1-mediated CSC regulatory mechanism could be inhibited by the common medicine aspirin, which can provide potential therapeutic opportunities for aggressive breast cancers." (PMID 29106390, 2018). "As opposed to these studies, in mammary tumors from MMTV-PyMT+/−; Sirt6+/− mice and in MDA-MB-231 cells with silenced SIRT6, we did not detect increased PDK1 or PDK4 expression." (PMID 33482921, 2021). "We showed a significant gain (p < 0.0001) in the expression of PDK1 and PDK3 in TNBC versus non-TNBC and in basal-like breast cancers relative to other subtypes such as luminal A, luminal B and HER2-enriched breast cancers." (PMID 33316932, 2020).